CTSH (cathepsin H)
Diseases named in the same sentence as CTSH in open-access papers (continued):
Sharing a sentence is not in itself a finding about the gene and the disease.
breast carcinoma (6 papers, 2014 to 2025). "Of the 92 quantified proteins only two shared similar up-regulations in breast cancer, dense breast tissue, and in premenopausal breasts namely CTSH and GAL." (PMID 37064098, 2023). "Only two proteins, pro-cathepsin H and galanin peptide, were similarly regulated in breast cancer, dense- and estrogen exposed breasts." (PMID 37064098, 2023). "This reverse MR analysis, which was performed only using the IVW method, revealed that in situ breast cancer could lead to an increase in cathepsin H expression (IVW: p = 0.037, OR = 1.184, 95% CI = 1.016-1.394)." (PMID 39944834, 2025). "The data of CTSH in breast cancer is sparse, but our results indeed show that this cathepsin may play a role in human breast cancer." (PMID 37064098, 2023). "An additional protein family of interest is the CTS proteins; in the present study, five CTS proteins (CTSB, CTSC, CTSD, CTSH and CTSZ) were identified to be upregulated in breast cancer." (PMID 24932247, 2014). "Although no data are available on the role of cathepsin H in MMTV-PymT breast cancer progression, cathepsin H depletion significantly impairs the establishment and maintenance of tumour vasculature and reduces the tumour burden in the RIP1-Tag2 model of pancreatic islet carcinogenesis." (PMID 37958596, 2023).
diabetes (6 papers, 2015 to 2025). "Interestingly, several studies suggested a potential link between elevated SIRPG and CTSH levels and diabetes susceptibility." (PMID 39408566, 2024). "In addition, patients who carry the protectively variant exhibited lower CTSH expression, higher HbA1c, and less diabetes remission." (PMID 33992646, 2021). "Importantly, the CTSH susceptibility allele is associated with faster disease progression in newly diagnosed diabetes and reduced beta cell function in healthy humans." (PMID 33515072, 2021). "As we have learned, some of the diabetes susceptibility genes e.g., GLIS3, PTPN2, BACH2 and Cathepsin H, regulate Bim expression." (PMID 26405162, 2015). "Given that CTSH genetic risk was associated with early diabetes onset and impaired beta-cell function independent of the human leukocyte antigen effect, our results highlight the importance of CTSH gene dysregulation in the natural history of T1D progression." (PMID 33992646, 2021).
hepatocellular carcinoma (6 papers, 2011 to 2024). A malignant tumor that arises from hepatocytes. "Among proteolytic enzymes, the cysteine cathepsin family member cathepsin H is also induced in TR-expressing hepatoma cells upon T3 treatment." (PMID 23878812, 2013). "Although TH/TR arguably has suppressor functions in hepatocellular carcinogenesis, in apoptosis-resistant hepatoma cells, TH/TR promotes tumor cell metastasis by upregulating several ECM proteases, such as furin, cathepsin H, and MMP, via TRAIL signaling." (PMID 23878812, 2013).
colorectal cancer (4 papers, 2000 to 2025). A primary or metastatic malignant neoplasm that affects the colon or rectum. "Our findings suggested the potential causalities of cathepsins S on colorectal cancer and cathepsin H on pancreatic cancer, indicating their potential as biomarkers and therapeutic targets in DSCs." (PMID 41026370, 2025). "In our study, we established a link between elevated SNP-predicted cathepsin S expression and an increased risk of colorectal cancer, while high cathepsin H levels might diminish pancreatic cancer risk." (PMID 41026370, 2025). "Cathepsin H-specific activity was significantly increased in colorectal cancers compared to control mucosa (P = 0.003;n = 77)." (PMID 10755408, 2000). "In contrast, cathepsin B and L activities analysed in the same paired extracts had been shown to be most frequently elevated in earlier stage carcinomas (Dukes' A and B), confirming that cathepsin H demonstrates a distinct pattern of expression during colorectal cancer progression." (PMID 10755408, 2000). "Our analyses of cathepsin H activity levels and protein forms in human colorectal cancers compared to matched control mucosa support the concept that altered proteinase expression patterns may reflect both cancer stage and site." (PMID 10755408, 2000).
lung adenocarcinoma (4 papers, 2024 to 2025). A carcinoma that arises from the lung and is characterized by the presence of malignant glandular epithelial cells. "CTSH is differentially expressed in the lungs of individuals at risk for lung adenocarcinoma when macrophages were examined suggesting a role in cellular proliferation in the lung." (PMID 40822650, 2025). "Subsequently, we utilized a two‐step method to analyze the mediating roles of these two metabolite traits in the causal pathway from CTSH to lung adenocarcinoma, using the delta method to estimate standard errors." (PMID 41473685, 2025). "We found that the indirect effect of DHA (22:6) levels in the causal pathway from CTSH to lung adenocarcinoma was 0.0009 (95% CI 4.3e‐5‐0.002, p = 0.0397), with a corresponding mediation proportion of 1.16% (95% CI 0.05% ‐ 2.26%)." (PMID 41473685, 2025). "Meta‐analysis of the IVW results from three databases showed a strong association between CTSH and lung adenocarcinoma (OR = 1.06, 95% CI = 1.02–1.10, P < 0.01), while lung squamous cell carcinoma lost significance (OR = 1.04, 95% CI = 1.00–1.08, P = 0.05)." (PMID 41473685, 2025). "We further utilized the recently released GWAS data for 233 metabolites to investigate their mediating roles between CTSH and lung adenocarcinoma." (PMID 41473685, 2025). "Collectively, more vigorously supporting the significant roles of DHA (22:6) levels and Omega‐3 fatty acids levels in CTSH‐related lung adenocarcinoma." (PMID 41473685, 2025). "Further colocalization analysis provided moderate evidence supporting the association of CTSH with omega‐3 fatty acid levels, as well as DHA levels and lung adenocarcinoma." (PMID 41473685, 2025). "This study suggests a possible link between CTSH and lung adenocarcinoma, with DHA (22:6) and Omega‐3 fatty acids identified as potential mediators." (PMID 41473685, 2025). "It was found that patients with lower risk scores responded better to immunotherapy and targeted therapies, and Cathepsin H emerged as a new protective biomarker for lung adenocarcinoma." (PMID 39451768, 2024). "In subsequent migration and invasion experiments, knocking down CTSH promoted the progression of lung adenocarcinoma." (PMID 39839650, 2024). "Surprisingly, we found no significant causal effects between CTSH and lung adenocarcinoma or lung squamous cell carcinoma, with p‐values remaining > 0.05 after BWMR and FDR corrections." (PMID 41473685, 2025). "However, the precise mechanism by which CTSH influences lung adenocarcinoma is presently unclear and warrants further investigation." (PMID 41473685, 2025). "Taken together, while current genetic and expression data suggest a possible pathogenic role of CTSH in lung adenocarcinoma, the evidence remains preliminary, and no definitive consensus has yet been reached." (PMID 41473685, 2025). "Additionally, CTSH and Omega‐3 fatty acids levels at chromosome 11 rs174564 had a PPH4 of 0.58, and DHA (22:6) levels and lung adenocarcinoma at chromosome 11 rs2524296 had a PPH4 of 0.76, providing moderate evidence for co‐localization (PPH4 > 0.5)." (PMID 41473685, 2025).
melanoma (4 papers, 2018 to 2024). A malignant, usually aggressive tumor composed of atypical, neoplastic melanocytes. "The analysis of this study indicates that cathepsin H reduces the risk of patients developing skin cancer, melanoma, and BCC." (PMID 39312365, 2024). "In summary, our MR analysis results suggest that the genetically predicted cathepsin H has an inhibitory effect on major subtypes of malignant skin tumors such as melanoma and CSCC, but further exploration is needed to understand its role in BCC." (PMID 39312365, 2024). "In the multivariate study, Cathepsin H demonstrated independent inhibitory effects on skin cancer (OR = 0.907, 95% CI: 0.830–0.992, P < .05) and melanoma (OR = 0.925, 95% CI: 0.862–0.993, P < .05)." (PMID 39312365, 2024). "In reverse Mendelian research, it was found that skin squamous cell carcinoma can increase the expression of Cathepsin H. Cathepsin E and Cathepsin O are also increased in melanoma and skin squamous cell carcinoma." (PMID 39312365, 2024). "In the reverse causal study, melanoma was found to cause an increase in cathepsin E (OR = 1.051, 95% CI: 1.011–1.093, P < .05), while CSCC was found to cause an increase in cathepsin H (OR = 1.154, 95% CI: 1.045–1.273, P < .05) and cathepsin O (OR = 1.111, 95% CI: 1.006–1.226, P < .05)." (PMID 39312365, 2024). "In the multivariate analysis, it was found that Cathepsin H is a direct factor in reducing the occurrence of skin cancer and melanoma, with no apparent causal relationship to non-melanoma skin cancer." (PMID 39312365, 2024). "Notably, cathepsin H demonstrates a potential protective effect against skin cancer, including melanoma and BCC, despite its elevated expression in squamous cell carcinoma." (PMID 39312365, 2024). "Here, we provide evidence that neutrophils may provide a source of cathepsin H in melanoma initiation." (PMID 29666124, 2018). "Research indicates that particular cathepsin proteins, such as Cathepsin L2, promote skin cancer, while others, like Cathepsin H, exhibit inhibitory effects on BCC and malignant melanoma." (PMID 39312365, 2024). "Cathepsin H was found to inhibit BCC (OR = 0.9587, 95% CI: 0.9275–0.9909, P < .05), melanoma (OR = 0.9335, 95% CI: 0.8729–0.9983, P < .05), and CSCC (OR = 0.961, 95% CI: 0.946–0.976, P < .05)." (PMID 39312365, 2024). "For example, it has been reported that overexpression of cathepsin H (CATH) is related to several pathological states, including carcinoma and melanoma." (PMID 32095334, 2020).
Alzheimer disease (3 papers, 2020 to 2025). A progressive, neurodegenerative disease characterized by loss of function and death of nerve cells in several areas of the brain leading to loss of cognitive function such as memory and language. "CTSH has also previously been linked with Alzheimer disease, where its expression in the temporal cortices of late-onset Alzheimer patients was shown to be altered." (PMID 32413284, 2020). "The CTSH gene was significantly associated with Alzheimer’s disease." (PMID 39228919, 2024). "CTSH has been implicated in the cis-regulated mRNA association with Alzheimer’s disease." (PMID 39228919, 2024). "In fact, the only fine-mapped pQTL we were able to replicate using this data was for CTSH (rs34593439), although this protein has yet to be linked with Alzheimer disease in whole blood analyses based on evidence from the EpiGraphdb platform (URL located in the Web Resources section)." (PMID 32413284, 2020). "In contrast, genes such as CTSH (which was also associated with Alzheimer disease) and SARM1 may make worthwhile therapeutic targets because they did not have genetically predicted effects on any of the other phenotypes after correcting for multiple testing." (PMID 32413284, 2020). "CTSH expression is significantly lower in the brain tissue of healthy controls than in patients with Alzheimer’s disease." (PMID 39228919, 2024). "In particular, SARM1 (p = 1.76 × 10−08 with amyotrophic lateral sclerosis) and CTSH (p = 5.57 × 10−05 with Alzheimer disease) represent the most promising candidates based on our evaluations." (PMID 32413284, 2020). "They highlight the unique ability of APP among neurodegenerative disease-relevant substrates to be cleaved by CTSA and CTSH, and underscore the importance of systematically profiling these enzymes to better understand their potential roles in Alzheimer’s disease." (PMID 40671818, 2025).
COVID-19 (3 papers, 2021 to 2025). A disease caused by infection with severe acute respiratory syndrome coronavirus 2. "Indeed, most recent proteomic analysis of COVID-19 autopsies suggested an overall upregulation of the cathepsin family members, including CTSB, CTSD, CTSE, CTSH, CTSK, CTSS, and CTSZ, in the lung of the COVID-19 patients." (PMID 34335974, 2021).
dementia (3 papers, 2022 to 2025). Loss of intellectual abilities interfering with an individual's social and occupational functions. "In conclusion, the genes CACNA1C, GABBR2, SCN2A, CTSH, MSRA, and SH3PXD2A may be associated with the neuro-progression of bipolar disorder to dementia." (PMID 39228919, 2024). "In conclusion, CACNA1C, GABBR2, SCN2A, CTSH, MSRA, and SH3PXD2A may be associated with the neuro-progression of bipolar disorder to dementia." (PMID 39228919, 2024). "Therefore, CTSH is a gene of interest related to bipolar disorder and dementia." (PMID 39228919, 2024). "The results showed that the genes CACNA1C, GABBR2, SCN2A, CTSH, MSRA, and SH3PXD2A were overlapping between patients with bipolar disorder and dementia." (PMID 39228919, 2024). "According to GWAS, the CACNA1C, GABBR2, SCN2A, CTSH, MSRA, and SH3PXD2A genes were common between bipolar disorder and dementia." (PMID 39228919, 2024). "As mentioned in the Results section, this second cluster includes genes that have also been related to other dementia types (e.g., GRN, TMEM107B, SNX1, MAPT, CTSB and CTSH)." (PMID 36066633, 2022).
glioma (3 papers, 2023 to 2025). A benign or malignant brain and spinal cord tumor that arises from glial cells (astrocytes, oligodendrocytes, ependymal cells). "Thus, we performed quantitative real-time PCR (qRT-PCR) analyses, which confirmed that CTSH, CTSO, CTSF, CTSK, CTSS, CTSV and CTSB were significantly downregulated in glioma cells treated with ar-turmerone." (PMID 37768200, 2023).
Cachexia (2 papers, 2019 to 2020). Severe weight loss, wasting of muscle, loss of appetite, and general debility related to a chronic disease. "Confirming these findings, the Walker-256 evolution, as an experimental model of cachexia, led to muscle wasting that occurred via the lysosomal and calcium-dependent pathways (increased cathepsin H and calpains activities) only in the W group, showing the effect of the cachexia in this group." (PMID 31200474, 2019).
diabetic retinopathy (2 papers, 2025 to 2026). "Both GSMR and univariable MR showed that Cathepsin H levels were causally associated with increased risks of overall diabetic retinopathy (DR), proliferative diabetic retinopathy (PDR), and diabetic maculopathy, validated by SMR and cis-eQTL MR analyses." (PMID 40616157, 2025). "In the UK Biobank (UKB), circulating CTSH was elevated in diabetic retinopathy and independently predicted incident disease." (PMID 42157922, 2026).
hippocampal atrophy (2 papers, 2021 to 2023). "However, cathepsin H deficiency decreases hypoxia-ischemia-induced hippocampal atrophy in neonatal mice through attenuation of TLR3/IFN-β signaling, suggesting that this pathway may be neuroprotective." (PMID 37124206, 2023).
Hyperglycemia (2 papers, 2025). An increased concentration of glucose in the blood. "Lysosomal protease activity regulation by glucose has been reported in metabolic studies, providing a mechanistic link between hyperglycemia and CTSH regulation." (PMID 41473685, 2025). "Although Cathepsin B/D have been implicated in hyperglycemia-anti-autophagic and pro-apoptotic effects under PDR, Cathepsin H’s specific role in retinal vascular pathology remains uncharacterized." (PMID 40616157, 2025). "Fasting hyperglycemia may contribute to elevated CTSH expression via hyperglycemia‐induced oxidative stress and inflammatory signaling pathways." (PMID 41473685, 2025).
pancreatic cancer (2 papers, 2022 to 2023). "For example, pro-cathepsin H, in its secreted form, enhances angiogenesis in pancreatic cancer, while secreted C-X-C motif chemokine 16 is a positive regulator of angiogenesis by acting as a T-cell attractor." (PMID 37443766, 2023).
proliferative diabetic retinopathy (2 papers, 2024 to 2025). Advanced retinopathy due to diabetes mellitus characterized by the formation of new vessels in the retina. "CTSH polymorphisms are associated with a reduced risk of progression to proliferative diabetic retinopathy." (PMID 39408566, 2024).
skin cancer (2 papers, 2014 to 2024). "Considering the results of the multivariate analysis and the bidirectional analysis, it is considered that Cathepsin H, L2, O, and B may have an impact on skin cancer and its subtypes." (PMID 39312365, 2024).
squamous cell carcinoma (2 papers, 2023 to 2024). A carcinoma arising from squamous epithelial cells. "Our results demonstrated only a weak causal link between cathepsin H levels and the risk of squamous cell carcinomas in univariable analysis using the IVW method." (PMID 37805623, 2023). "Additionally, weaker positive effects were observed for cathepsin H levels and the risk of squamous cell carcinomas, and cathepsin G levels and the risk of adenocarcinoma, respectively, only by the IVW method (p = 0.032, OR = 1.053, 95% CI = 1.005–1.104; p = 0.041, OR = 1.095, 95% CI = 1.004–1.195)." (PMID 37805623, 2023). "However, high expression of cathepsin H is observed in squamous cell carcinoma." (PMID 39312365, 2024). "However, observational research has indicated that cathepsin H is most significantly associated with squamous cell carcinomas, an association not supported by the current MR analyses." (PMID 37805623, 2023). "However, there was horizontal pleiotropy in the effect of Cathepsin H on squamous cell carcinoma (P < .05), and in this study, it is not considered that Cathepsin H can inhibit squamous cell carcinoma." (PMID 39312365, 2024).
thyroid cancer (2 papers, 2022 to 2023). "High serum levels of CTSH in lung- and thyroid cancer have been associated with good prognosis whereas high blood and tissue levels in lung- and gall bladder cancer are associated with decreased survival." (PMID 37064098, 2023).
Autoimmunity (1 paper, 2021). The occurrence of an immune reaction against the organism's own cells or tissues. "Although CTSH-null mice do not demonstrate gross developmental defects, CTSH was associated with autoimmunity in mouse models and humans including experimental autoimmune encephalomyelitis and T1D." (PMID 33992646, 2021).
basal cell carcinoma (1 paper, 2024). A carcinoma involving the basal cells. "CTSH is a lysosomal cysteine protease involved in the degradation of extracellular matrix components and has been found to be more active in basal cell carcinoma tumors than in normal skin tissue." (PMID 38883596, 2024). "The mechanism underlying the involvement of CTSH in the development of basal cell carcinoma has not yet been investigated." (PMID 38883596, 2024).
bipolar disorder (1 paper, 2024). A disorder of the brain that causes unusual shifts in mood, energy, activity levels and the ability to carry out day-to-day tasks. "in a Bulgarian population identified a significant association between bipolar disorder and CTSH." (PMID 39228919, 2024).
bladder cancer (1 paper, 2023). "Despite the report that CTSH increased the chemoresistance of bladder cancer, here, for the first time, we have described a CTSH-mediated survival mechanism after IR in HCC cells that substantially contributes to radioresistance." (PMID 36982347, 2023).
Cerebral ischemia (1 paper, 2021). Restriction of arterial blood supply to the brain associated with insufficient oxygenation to support the metabolic requirements of the tissue. "Cathepsin H immunoreactivity in the hippocampus is increased in an animal model of cerebral ischemia, and cathepsin H activity increases in affected brain areas in Huntington’s disease." (PMID 34944440, 2021).